TNF (tumor necrosis factor)
Diseases named in the same sentence as TNF in open-access papers (continued):
Sharing a sentence is not in itself a finding about the gene and the disease.
Sepsis (continued). "Once again, over-activation of the innate immune system plays a key role and is the basis of the pathogenic processes in the development of septic cardiomyopathy mediated by DAMPs and PAMPs at the onset of sepsis, which triggers a cytokine storm (TNFα, IL-1, IL-6)." (PMID 39941634, 2025). "In sepsis, a large number of proinflammatory cytokines (TNF- α, IL-6, IL-1 β) are released, triggering a cascade of inflammatory responses, leading to cardiomyocyte damage, mitochondrial collapse, deregulation of calcium homeostasis and, ultimately,myocardial contractile dysfunction." (PMID 40276499, 2025). "NF‐κB activation results in the production and release of various pro‐inflammatory cytokines, such as tumor necrosis factor‐alpha (TNF‐α), interleukin‐1 alpha (IL‐1α), IL‐6, and IL‐8, which contribute to the cytokine storm and systemic inflammation during sepsis." (PMID 40599085, 2025). "TNF not only exacerbates kidney damage by enhancing the immune response but may also worsen sepsis progression by promoting immunosuppression." (PMID 40166075, 2025). "Indeed, overproduction of circulating levels of IL-6, TNFα, and IL-10 were accompanied by the development of hypothermia during different animal models of sepsis." (PMID 40534875, 2025). "Interestingly, there is a significant overlap in the pathways of aberrant activation observed in macrophages from IBD patients and monocytes from sepsis patients, including the IL‐17 signalling pathway, complement activation and TNF signalling pathway." (PMID 39993996, 2025). "Having a higher TNF-α to IL-10 ratio is beneficial in sepsis survivors with weakened immune systems, as an earlier clinical study showed that a sustained overproduction of IL-10 is a predictor of sepsis severity and worsened outcomes." (PMID 41124072, 2025). "The previous study of our research group confirmed that DCHD significantly could reduce serum inflammatory factor levels (e.g., IL-1β, TNF-α, IL-6) in rats with sepsis induced by cecal ligation and puncture." (PMID 41378216, 2025). "In sepsis patients, the increased TNF-α and IL-6 levels indicate severe inflammatory response." (PMID 41393152, 2025). "In sepsis, DPEP2 is closely related to macrophage function, and its deficiency leads to excessive production of pro-inflammatory factors (such as TNF-α and IL-6), highlighting its importance in inhibiting macrophage overactivation and maintaining immune homeostasis." (PMID 41359645, 2025). "Still, anti-TNF therapy in sepsis has only shown a modest increase in the survival." (PMID 40064845, 2025). "It has been reported that RDW is associated with inflammatory response, oxidative stress, and tumor necrosis factor‐α (TNF‐α) and may serve as a robust predictor of various diseases, including acute ischemic stroke, acute pancreatitis, and sepsis." (PMID 41022427, 2025). "Sepsis is characterized by hyperinflammatory response, marked by the excessive release of cytokines such as interleukin (IL)−1β, IL-6, and tumor necrosis factor-α (TNF-α), as well as multiple organ dysfunction syndrome (MODS), which affects the heart, liver, kidneys, lungs, spleen, and brain." (PMID 40461967, 2025). "Administering serum EVs derived from a mouse model of sepsis produced by lipopolysaccharide (LPS) enhanced the microglial cell activation, the proliferation of astrocytes, and elevated production of IL‐6 and TNF‐α in the hippocampus and cerebral cortex of healthy mice." (PMID 40537921, 2025). "Additionally, broad-spectrum metalloprotease/TACE inhibition has been shown to attenuate TNF-α release and protect against endotoxin-induced organ injury in preclinical sepsis models." (PMID 41465816, 2025). "However, TNFα levels increase markedly in the setting of clinical sepsis and acquire a circadian rhythm that peaks at night in human serum and during the rest phase in rat hippocampal microglia." (PMID 39968295, 2025).
Sepsis (continued). "Additionally, the antagonist CID16020046 significantly decreases the production of pro-inflammatory cytokines TNF-α and IL-6 and reduces leukocyte adherence in the submucosal venules of the intestines during experimental sepsis." (PMID 40429822, 2025). "Both PCT and TNF-α have value in the diagnosis and monitoring of sepsis." (PMID 38709460, 2024). "The potential causes could be associated with dexmedetomidine in reducing the generation of sepsis-triggered inflammatory substances, such as TNF-α and IL-6, and preventing apoptosis (ClinicalTrials.gov ID NCT01760967)." (PMID 38816685, 2024). "TNF-α is a key mediator of sepsis that can induce kidney injury by activating TNF receptors." (PMID 39330225, 2024). "While we are not aware of a role for microbiota in sperm or testosterone production, we have previously noted that insults, such as microbiota depletion or sterile sepsis induced by TNF administration, alter the expression of necroptotic effectors in other tissues." (PMID 39572538, 2024). "Together, these results suggest that Tim3 expression and TNF signaling may also be relevant for NK cells in human diseases, including sepsis." (PMID 39543125, 2024). "“Reversal of immune paralysis” was hypothesized to explain enhanced peripheral blood TNF and IL-6 responses in two clinical trials of macrolide therapy in patients with sepsis." (PMID 39284999, 2024). "Indeed, the immunomodulatory activity of LF was observed 24 h after sepsis induction at the inflammatory site, as evidenced by the reduction in TNF-α and TGF-β levels." (PMID 39199173, 2024). "Furthermore, the TNF-α/IL-10 ratio decreased in both groups (CLP+LF and CLP+LF-ERTA), suggesting a potential reduction in the inflammatory process associated with sepsis." (PMID 39199173, 2024). "Immunomodulatory agents may hold promise, given the significance of TNF-α and IL-1β as sepsis mediators." (PMID 39200042, 2024). "Additionally, the production of sepsis stimulates an inflammatory response, encouraging the release of pro-inflammatory cytokines (IL-6 and TNF-), which in turn increases the amount of reactive oxygen species." (PMID 39394109, 2024). "Furthermore, in sepsis, B cells can produce a variety of pro-inflammatory cytokines like IL-6, TNF, IL-3, and GM-CSF to reinforce the systemic inflammatory response." (PMID 38474403, 2024). "Bacterial lipopolysaccharide (LPS) is known to be able to stimulate the production of many proinflammatory mediators and proteins, such as iNOS, TNF-α, IL-6 and COX-2, in various inflammatory cells and to cause the physiological responses of inflammation, sepsis and stroke." (PMID 38392528, 2024). "TNFα has long been considered as a primary offensive molecule in sepsis severity and mortality." (PMID 38966542, 2024). "Sepsis can lead to the excessive production of pro-inflammatory cytokines such as interleukin-6 (IL-6), interleukin-1 beta (IL-1β), and tumor necrosis factor-alpha (TNF-α)." (PMID 39273060, 2024). "In the early stages of sepsis, macrophages become overactivated, resulting in an increase of pro-inflammatory M1 macrophages and the release of a large number of inflammatory cytokines (such as IL-1, IL-6, TNF-α, and iNOS)." (PMID 38715602, 2024). "Similarly, Kupffer cells from rats with CLP-induced sepsis had a significant increase in the concentration of TNF-α, accompanied by an increase in ICAM-1 mRNA levels in the whole-liver tissue." (PMID 38254684, 2024). "Perindopril prevents sepsis-induced acute kidney injury by reducing plasma TNF-α levels." (PMID 38685954, 2024). "This is the first study to show that the in vitro production of TNF-α and IL-6 by preterm neonatal WB at birth is comparable to term neonatal WB and adult WB after exposure to a broad range of stimuli that are relevant during neonatal sepsis." (PMID 38562936, 2024). "However, the administration of ghrelin immediately after induction of sepsis significantly lowered TNF-α levels compared to sepsis and vehicle groups." (PMID 39144689, 2024).
Sepsis (continued). "In the context of sepsis, ghrelin administration has been shown to improve myocardial contractility and ventricular peak systolic pressure, potentially through direct actions on the ventricles and by reducing the levels of proinflammatory cytokines like TNF-α." (PMID 39144689, 2024). "The mechanism by which TNF contributes to the global milieu of sepsis and how it may relate to clinical outcomes, however, remains ambiguous." (PMID 39469706, 2024). "Additionally, the control group showed decreased intestinal barrier permeability, lower plasma levels of inflammatory factors (IL-1β and TNF-α), and heightened protein expression of mechanical barrier markers like ZO-1 in contrast to the sepsis feces group." (PMID 39026673, 2024). "During the hyperinflammatory phase of sepsis, macrophages play a crucial role in monitoring the infection through their ability to phagocytose bacteria, present antigens, and produce significant amounts of cytokines such as TNF-α, IL-6, and IL-1β." (PMID 38799158, 2024). "The association with leukocyte transendothelial migration, TNF signaling pathway and PI3K-Akt signaling pathway indicated that PGK1 may contribute to the dysregulated immune response observed in sepsis." (PMID 39712033, 2024). "Here, we tested the hypothesis that ex vivo functional TNF expression as well as an immunologic endotype based on both IFNγ and TNF expression could be used to model clinical outcomes in sepsis patients." (PMID 39469706, 2024). "Furthermore, consistent with our findings, a positive association between Bacteroidales and the proinflammatory cytokine TNF-α was identified, with TNF-α known to be associated with the progression of sepsis." (PMID 38698853, 2024). "Vincamine exhibited hepato-protective potential during CLP-induced sepsis via the cross-connection of antioxidant, anti-inflammatory, and anti-apoptotic activities by modulating TNFα/IL-6/IL-1β/Nrf-2/Keap-1 and regulating bax/bcl2/cleaved caspase 3 signaling pathways." (PMID 39174578, 2024). "Similarly, high TNF-α levels in a model of sepsis induce memory deficits that are diminished after the administration of a TNF-α inhibitor." (PMID 39595890, 2024). "In an experimental model of sepsis induced by cecal ligation, female mice exhibit higher survival rates and maintain splenocyte functions, whereas male mice release higher levels of IL-6, TNF-α, and prostaglandin E2 (PGE2)." (PMID 38835761, 2024). "Furthermore, the specific deficiency of TREM2 in macrophages decreased the production of IL-6, IL-1β, and TNF-α in the lung of sepsis mice." (PMID 39405126, 2024). "We analyzed whether the polymorphism was correlated with the cytokine expression of IL1β, IFNα2, IFNγ, TNF-α, IL-33, IL12p70, MCP-1, IL-6, IL-10, IL-17a, IL-18, or IL-23 to further investigate the effect of the polymorphism in sepsis patients." (PMID 38338680, 2024). "In this study, we tested the hypothesis that whole blood ex vivo functional TNF expression alone as well as an immunologic endotype based on both IFNγ and TNF expression could be used to identify clinical outcomes in sepsis patients." (PMID 39469706, 2024). "TNF-α is one of the earliest and most extensively studied cytokines in the context of sepsis." (PMID 39056754, 2024). "During sepsis, pulmonary cells (namely pulmonary macrophages) secrete pro-inflammatory cytokines (mainly TNF-α), and it is reasonable to assume that secretion of these mediators increased when removal of bacteria and associated products such as endotoxin by Kupffer cells was inhibited." (PMID 38254684, 2024). "Therefore, LPS mediated renal tissue apoptosis through inflammatory factors, mainly TNF-α, is an important pathological pathway of renal injury in sepsis mediated AKI." (PMID 39238634, 2024).
Sepsis (continued). "Consequently, our results highlight the remarkable ability of LBT to downregulate the production of IL-6, TNF-α, and IL-1β while alleviating LPS-induced sepsis through its impact on macrophage-mediated inflammatory cytokine production." (PMID 38799158, 2024). "Additionally, sepsis is characterized by increased release of pro-inflammatory cytokines, such as IL-1β, IL-6, and TNF-α." (PMID 39337575, 2024). "Finally, after multivariate logistic regression analysis, MPO, HOCl, TNF-α, WBC, and APACHE II score were identified as independent risk factors for NOAF in sepsis." (PMID 39030470, 2024). "Additionally, the levels of pro-inflammatory cytokines, such as IL-17A, IL-6, and TNF-α, were notably elevated in the Sepsis+shPIMI group, whereas the anti-inflammatory cytokine IL-10 was reduced." (PMID 39108261, 2024). "In sepsis, although the levels of t-PA and u-PA increase, but TNF-α and IL-1 may increase the expression of PAI-1, leading to an overall fibrinolysis inhibition." (PMID 39252831, 2024). "As expected, levels of IL-6 and TNF-α in the plasma were increased in the setting of sepsis." (PMID 38957471, 2024). "FITC, IL-1β, TNF-a and D-lactic acid levels were significantly elevated in the sepsis group." (PMID 39026673, 2024). "Additionally, men with multiple injuries and those who develop post-trauma sepsis produce increased levels of IL-6, IL-8, and TNF-α." (PMID 38835761, 2024). "During this pathophysiological process, inflammatory factors such as IL6, TNF-a, and neutrophils may trigger an “inflammatory factor storm,” leading to sepsis-related sequential organ failure." (PMID 38765257, 2024). "Macrophages serve as major producers of TNF-α in sepsis and in early stage of sepsis-induced ALI." (PMID 39134731, 2024). "lncRNA-HOTAIR enhances the production of TNF-α in LPS-induced sepsis in mice." (PMID 39113804, 2024). "Additionally, our findings demonstrated that LBT effectively downregulated the levels of IL-6, TNF-α, and IL-1β in serum samples while inhibiting inflammatory cell infiltration within lung and liver tissues induced by LPS-induced sepsis." (PMID 38799158, 2024). "While the use of laboratory testing to quantify TNF has demonstrated efficacy as a screening tool for clinical sepsis, it is not routinely used in a diagnostic or prognostic capacity." (PMID 39469706, 2024). "Importantly, TNF recovery occurred more rapidly in sepsis patients (p = 0.041), driven primarily by differences in the concentration of this cytokine at 24 h (p <0.001) and 168 h (p = 0.001) of critical illness." (PMID 39712015, 2024). "Plasma TNF-α levels are significantly increased in patients with sepsis and septic shock." (PMID 38716051, 2024). "By using anti-MIF antibodies to neutralize MIF, it has been demonstrated that TNF-α production and the build-up of neutrophils can be reduced, resulting in the alleviation of symptoms and improved prognosis for sepsis-related ARDS patients, ultimately reducing the likelihood of mortality." (PMID 38745657, 2024). "TNF is a pleiotropic pro-inflammatory cytokine that drives cytokine production/survival or cell death and thus is involved in many processes, including embryonic development and sepsis." (PMID 37855658, 2024). "The antibody treatment exerted anti-inflammatory effects via simultaneous inhibition of IL-6, CXCL8/IL-8, CCL3/MIP-1, TNF-α, and IFN-γ production, and had direct and considerable suppressive effects on excessive CCL and CXCL gene expression associated with sepsis immunopathogenesis." (PMID 38177528, 2024). "Additionally, pretreatment with GdCl3 in CLP-induced sepsis significantly increased the expression of various cytokines, including TNF-α, and increased the MPO activity and infiltration of leukocytes in the lung tissue." (PMID 38254684, 2024). "In the bone marrow, we confirmed that TNF plus IL-1β are sufficient to decrease the abundance of cell types from the erythroid lineage, which help to explain anemia, a well-described phenomenon in sepsis." (PMID 38191855, 2024).
Sepsis (continued). "In vivo, TRAIL-encapsulated nanogel significantly reduced TNF-α and IL-6 levels, blood bacterial load, and pulmonary leukocytes accumulation; thus, it protected mice against K. pneumoniae-induced sepsis and LPS-induced lung and kidney injury and prolonged their survival rates." (PMID 38637839, 2024). "The three major pro-inflammatory cytokines TNF-α, IL-1β and IL-6 were not specific for sepsis and their primary role as biomarkers of sepsis appears to be prognostic rather than diagnostic." (PMID 38643461, 2024). "-Let-7a acts as a TLR4 antagonist.-Let-7a is correlated with reduced TNF alpha, interleukin1β, and TLR signaling in an LPS-induced manner.-Levels of let-7a is associated with the regulation of the TLR-mediated immune response in sepsis." (PMID 38756232, 2024). "Importantly, two studies showed that the rs12692386 A > G allele of ADAM17 increased the protease expression and shedding of TNF, IL-6R, and CX3CL1, conferring a higher risk of severe disease and shock in sepsis." (PMID 38881671, 2024). "Furthermore, TNFα expression was also suppressed by α-GalCer pretreatment in the spleen and liver during LPS/D-GalN-induced sepsis." (PMID 39355237, 2024). "In animal models, it has been demonstrated that OMVs derived from intestinal E. coli are causative microbial signals in the pathogenesis of systemic inflammatory response syndrome (SIRS) and sepsis-induced lethality through the systemic induction of TNF-α and IL-6." (PMID 39201409, 2024). "Levels of serum IL-6, TNF-α, and IL-10 in sepsis mice treated with anti-PD-L1 antibody significantly declined at 24 (P = 0.004), 48 (P = 0.006), and 72 h (P = 0.005), respectively; there were no significant changes at other time points, showing no statistical significance." (PMID 37776443, 2024). "Similarly, numerous reports note elevation in serum concentrations of IL-1β, IL-6, IL-8, and TNF-α between neonatal individuals with sepsis and the corresponding control cohorts." (PMID 38510969, 2024). "Similarly, anti-TNF-α drugs, which are effective in treating chronic diseases like rheumatoid arthritis, have been considered as potential targets in animal models of sepsis." (PMID 38294676, 2024). "Sepsis is characterized by an inflammatory response triggered by infections, leading to the release of proinflammatory cytokines such as interleukin-1beta (IL-1β), IL-6, and TNF-α." (PMID 38629103, 2024). "Clinical trials have attempted to neutralize TNF in the context of sepsis with mixed results, however, a meta-analysis suggested that this type of therapy could reduce overall mortality." (PMID 39543125, 2024). "In vivo studies demonstrated that HIPK2-deficient mice are more susceptible to lipopolysaccharide (LPS)-induced endotoxemia and cecal ligation and puncture (CLP)-induced sepsis, with increased serum concentration of proinflammatory IL-6, IL-1β and TNF-α cytokines." (PMID 39062921, 2024). "Why is TNF the central node of this cytokine module recapitulating many of the effects of sepsis?" (PMID 38191855, 2024). "In other studies, it has been proposed that different pro-inflammatory markers such as tumor necrosis factor-α (TNF-α), interleukin (IL)-1, IL-6, and IL-8 are increased in sepsis and may lead to an increase in thrombocyte production." (PMID 39417064, 2024). "Sepsis is characterized by two distinct phases: an initial hyper-inflammatory phase characterized by a remarkable surge in potent cytokines like TNF-α and IL-6, followed by an immunosuppression phase wherein inflammatory cytokines levels significantly decrease." (PMID 38348451, 2024). "Moreover, the elevated NGAL and KIM‐1 levels in serum, TNF‐α, IL‐6, and IL‐1β levels in the kidneys in sepsis group were partly reversed by LV‐shMALAT1." (PMID 39390627, 2024).